RN7SL445P (RNA, 7SL, cytoplasmic 445, pseudogene)
Gene: Miscellaneous RNA gene on chromosome 10 (5,631,463 to 5,631,755, forward strand). Ensembl gene ENSG00000240577.
Homologues: Orthologues: chimpanzee Metazoa_SRP (98% identical), macaque Metazoa_SRP (92% identical). Paralogues in human: RN7SL1 (82% identical), RN7SL2 (81% identical), RN7SL3 (81% identical), RN7SL147P (80% identical), RN7SL597P (79% identical), RN7SL664P (79% identical), RN7SL709P (78% identical), RN7SL448P (77% identical), RN7SL493P (77% identical), RN7SL566P (77% identical), RN7SL804P (77% identical), RN7SL126P (77% identical), and 701 more.